RAF1 (Raf-1 proto-oncogene, serine/threonine kinase)
Diseases named in the same sentence as RAF1 in open-access papers (continued):
Sharing a sentence is not in itself a finding about the gene and the disease.
Noonan syndrome (continued). "Specifically, pathogenic heterozygous variants in RAF1 cause LEOPARD syndrome 2 and Noonan syndrome 5 in humans (OMIM 164760), where affected patients have, among other features, short stature, dolichocephaly, hypertrophic cardiomyopathy, pulmonary valve stenosis, and neurodevelopmental delay." (PMID 40525707, 2025). "In addition to the PTPN11 mutations in the RAS‐MAPK signaling pathway, including KRAS, SOS1, RAF1, SHOC2, NRAS, BRAF and CBL, can also cause Noonan syndrome." (PMID 37525886, 2023). "In Noonan syndrome, gain-of-function mutations in PTPN11 (12q24.13), NRAS (1p13.2), SOS1 (2p22.1), RAF1 (3p25.2), BRAF (7q34), KRAS (12p12.1), and MAP2K1 (15q22.31) genes may activate the Ras-Raf-MEK-ERK signaling pathway." (PMID 34539540, 2021). "Meanwhile, prolonged activation of PI3K/AKT and ERK signaling disrupts the regulation of cell growth and division, leading to the characteristic features of Noonan syndrome (OMIM# 163950) that is caused by germline variation in KRAS genes (PTPN11, SOS1, RAF1, LZTR1, etc.)." (PMID 31752936, 2019). "For example, studies of Noonan Syndrome-associated cardiac defects reveal that hypertrophic cardiomyopathy is observed in less than 20% of cases linked to PTPN11/SHP2 or SOS1 mutations, but greater than 90% of RAF1 mutations." (PMID 31017896, 2019). "Individuals with Noonan Syndrome (MIM: 163950) comprise ~50% of all RASopathy cases and mutations have been observed in multiple genes, including PTPN11/SHP2, SOS1, SHOC2, KRAS, NRAS, LZTR1 (MIM: 600574), RAF1/CRAF, and MAP2K1/MEK1." (PMID 31017896, 2019). "In addition, we verified by exomeanalysis that the patient did not have any pathogenic variants in the genes associatedwith Noonan Syndrome and other rasopathies (PTPN11,SHOC2, KRAS, CBL,SOS1, RAF1, HRAS,NRAS, RASA1, SPRED1,BRAF, MAP2K1, MAP2K2, RIT1 andRRAS)." (PMID 27561113, 2016). "In the absence of SH3BP2 mutation in an individual considered to have Cherubism, genetic screening for mutations in genes implicated in Noonan syndrome (PTPN11, SOS1, RAF1, KRAS, NRAS, and BRAF), NF1, and craniofacial cutaneous syndrome (BRAF, MAP2K1) should be undertaken." (PMID 25409853, 2014). "A small proportion of individuals with Noonan syndrome also exhibit multiple gnathic GCG previously reported as Noonan-like/multiple GCG, but this phenotype is now recognized to be allelic with Noonan syndrome, as mutations in PTPN11, SOS1, and RAF1 have been reported in this syndrome." (PMID 25409853, 2014). "Interestingly, the remaining genes found to result in the clinical features of Noonan syndrome also involve the Ras-MAP kinase signaling system, including mutations in KRAS, SOS1 and RAF1." (PMID 22011734, 2011). "Mutations in the following genes that cause Noonan syndrome have been identified: RAS family GTPase proteins (KRAS, NRAS, RIT1, and RRAS), RAS signal function modulators (PTPN11, SOS1, SOS2, CBL, RASA2, and SHOCS2), and downstream signal transducers (RAF1 and BRAF)." (PMID 38248880, 2023). "No mutation was found in exon 7 of RAF1, which is a hotspot for mutations in Noonan syndrome (NS)." (PMID 18925961, 2008). "Over the years, several other genes involved in Noonan syndrome (KRAS, SOS1, RAF1, MAP2K1, BRAF, NRAS, RIT1, and LZTR1) have been identified, acting at different levels of the RAS-mitogen-activated protein kinase pathway." (PMID 38254922, 2023). "While the phenotypes of many mutant mouse models correlate with human patients, the discrepancies with Raf1, SOS1, or other genes suggest more information is needed to understand how these genes influence Noonan syndrome phenotypes and how the pathway as a whole regulates nervous system function." (PMID 38463630, 2024).
Noonan syndrome (continued). "Gene sets in protein phosphorylation and JUN-MAPK (mitogen-activated protein kinase) cascades were also enriched but not entirely due to three Noonan syndrome genes (PTPN11, BRAF, RAF1)." (PMID 30532227, 2018).
lung carcinoma (53 papers, 2009 to 2026). "Many factors including EGFR, HIF-1A, AKT1 and RAF-1 are known to be regulated by Hsp90 and their abnormal expression level is often associated with lung cancers." (PMID 21283735, 2011). "Finally, rescue assays delineated that overexpression of RAF1 partially rescued FBXL19-AS1 knockdown-mediated inhibition of lung cancer progression and the expression of angiogenesis associated proteins." (PMID 30610161, 2019). "Key genes, including MAPK1, RAP1B, and RAF1, featured prominently in these pathways, underscoring their functional relevance in lung cancer." (PMID 38391911, 2024). "Mitogen-activated protein kinase (MAPK) plays an important role in the development of lung cancer, among which k-ras and RAF-1 are studied in-depth in targeted therapy." (PMID 37107587, 2023). "To explore the potential anti-tumor targets of apatinib, we have examined all tyrosine kinases and important silk/threonine kinases associated with lung cancer including Akt 1-3, FRAP1, PIK3C2A, PIK3C2B, BRAF, BRAF V600E and RAF1 in the Life platform." (PMID 36759818, 2023). "Another study proved that FBXL19-AS1/miR-431-5p/RAF1 axis functions as an oncogenic pathway and plays an effective role in lung cancer." (PMID 36649030, 2022). "OIP5 (Opa interacting protein 5), one of the cancer-testis antigens, is involved in cell cycle regulation and interacts with RAF1 in lung cancer, resulting in poor prognosis." (PMID 36498802, 2022). "FBXL19-AS1 was also shown to exert a tumorigenic role in leading the progression and angiogenesis by sponging miR-431-5p to regulate RAF1 expression in lung cancer." (PMID 36649030, 2022). "In KRAS-driven lung cancer, targeting of RAF1 was suggested to be a tumor-selective strategy since RAF1 was found to be essential for tumor initiation." (PMID 35965494, 2022). "Fatherly, we discovered that RAF1 expression was down-regulated in miR-431-5p mimic transfected lung cancer cells by Western blot." (PMID 30610161, 2019). "RAF1 overexpression partially rescued FBXL19-AS1 knockdown-mediated inhibition of lung cancer angiogenesis and progression." (PMID 30610161, 2019). "Molecular mechanism exploration uncovered that FBXL19-AS1 acted as a molecular sponge of miR-431-5p and that RAF1 was a downstream target of miR-431-5p in lung cancer." (PMID 30610161, 2019). "Together, these results indicated that FBXL19-AS1 was involved in progression and angiogenesis in lung cancer by targeting miR-431-5p/RAF1 axis, which provided a new insight into the therapeutic strategies of lung cancer." (PMID 30610161, 2019). "Previous studies have indicated that Raf1 was a target of miR-431-5p and functioned as a promoter in angiogenesis and progression of lung cancer." (PMID 31870440, 2019). "Inhibition of Ras activity by HAMLET in lung carcinoma cells was demonstrated by co-immunoprecipitation of active Ras with the Ras-binding domain of Raf1." (PMID 26561036, 2015). "In another study by Schuller and Cekanova, NNK is reported to stimulate β2-AR receptor pathway (including PKA, cAMP, CREB) and transactivate EGFR pathway (such as Raf-1/ERK1/2 signaling) in the development of lung cancer." (PMID 21559255, 2011). "There is also evidence for Raf-1 overexpression in human lung adenocarcinomas and in a recent report c-Raf was shown to antagonize apoptosis induced by IFNα in human lung cancer cells." (PMID 19812696, 2009).
lung carcinoma (continued). "Moreover, invasive property of lung cancer cells A549 was significantly increased on RAF1 transfection." (PMID 33931671, 2021). "In addition, a recent study has reported that the down-regulation of RAGE by small interfering RNA (siRNA) inhibits migration and invasion through negatively regulating PI3K/AKT and KRAS/RAF-1 signaling cascades in lung cancer H1975 cells." (PMID 32327633, 2020). "Finally, we proved that FBXL19-AS1 regulated angiogenesis and tumor progression in lung cancer through miR-431-5p/RAF1 axis." (PMID 30610161, 2019). "In the present study, we planned to investigate whether lncRNA FBXL19-AS1 exerted the oncogenic role in angiogenesis and progression of lung cancer via miR-431-5p/RAF1 axis." (PMID 30610161, 2019). "Our data also build on a recent report by Rai and co-workers in which delivery of miR-7 to EGFR inhibitor-resistant lung cancer cells suppressed growth in vitro and in vivo, an effect that was associated with decreased expression of EGFR as well as its downstream kinases RAF1 and IRS1." (PMID 23115635, 2012). "A previous study found that romidepsin treatment of human lung carcinoma cell lines reduced the steady-state levels of various signaling proteins, including Raf-1, which may account for inhibition of ERK signaling." (PMID 19682393, 2009). "For instance, the downregulation of miR-7, which has an aberrant expression pattern in lung cancer, has been demonstrated to inhibit the mRNA expression of EGFR and Raf1." (PMID 38355480, 2024). "Indeed, these kinase-independent functions of RAF1 are strongly supported by in vivo experiments involving two distinct knock-in alleles encoding truly kinase-inactive RAF1 proteins and failed to recapitulate the protective effect of the loss of RAF1 expression in a lung cancer model." (PMID 39120280, 2024). "The results show that KFC play an important therapeutic role in the treatment of lung cancer by targeting Ras, AKT, IKK, Raf1, MEK, and NF-κB in the PI3K-Akt, MAPK, SCLC, and NSCLC signaling pathways active in lung cancer." (PMID 37189139, 2023). "Analysis of human lung cancer data sets derived from The Cancer Genome Atlas (TCGA) showed that KRAS, RAF1, MAP2K1, MAP2K2, MAPK3, and MAPK1 expression levels were positively correlated with the BCL6 expression level." (PMID 36377663, 2022). "NNK has also been shown to activate the β2-adrenergic receptor, which transactivates the EGFR and Raf-1/ERK1/2 signaling cascades, both of which are also well characterized for their roles in lung cancer progression and metastasis." (PMID 33351788, 2021). "Then, the co-transfection of pcDNA3.1/RAF1 reversed the inhibitory roles of sh-FBXL19-AS1 in the proliferation, migration, and invasion of lung cancer cells." (PMID 30610161, 2019). "Through rescue experiments, we discovered that overexpression of RAF1 partially rescued FBXL19-AS1 knockdown-mediated inhibition of angiogenesis and progression in lung cancer." (PMID 30610161, 2019). "It has been reported that both nicotine and 4-(Methylnitrosamino)-1-(3-pyridyl)-1-butanone (NNK) are able to induce lung cancer by binding to nAChR and activating PKC, Raf1, AKT, ERK1/2, and transcription factors such as Jun, Fos, and c-Myc." (PMID 22662279, 2012). "It has been demonstrated that nicotine or NNK stimulated lung cancer cell proliferation via α7 nAChR with activations of PKC, RAF1, AKT, ERK1/2, and transcription factors such as JUN, FOS, and MYC." (PMID 21559255, 2011). "miR-7 targets RAF1, IRS-2, BCL-2, and PA28γ in lung cancer cells." (PMID 33422052, 2021). "We provide specific and previously undescribed data on fusions involving RAF1, ROS1, and BRD4 that suggest that existing drugs could be repurposed for use in rare pancreatic, breast, and lung cancers." (PMID 31097696, 2019). "Moreover, the expression level of RAF1 was significantly up-regulated in lung cancer tissues compared with non-tumor tissues." (PMID 30610161, 2019).
pancreatic cancer (44 papers, 2010 to 2026). "We next examined the effects of KRB-456 on the levels of KRAS bound to GTP and on the binding of KRAS to RAF1 in intact Panc0203 and Panc1 human pancreatic cancer cells that harbor mt KRAS G12D." (PMID 38051103, 2023). "Among the 10 RAF1 fusion (+) patients, one patient with pancreatic cancer had an MSI-H tumor and high TMB." (PMID 38137485, 2023). "Activation of the RAF1/MEK/ERK pathway is induced by PEBP1 degradation in pancreatic cancer and promotes the migration and invasion of pancreatic cancer cells." (PMID 34222329, 2021). "RAF1 accelerates migration and invasion of pancreatic cancer and disorders of the RAF1 pathway are related to worse prognosis in pancreatic cancer patients." (PMID 33302876, 2020). "Together, our analysis supports emerging evidence for rare recurrent and potentially therapeutically actionable RAF1 rearrangements in KRAS wild-type pancreatic cancer." (PMID 31097696, 2019). "Components of the pancreatic cancer pathway were extensively S-nitrosylated, such as v-raf-1 murine leukemia viral oncogene homolog 1 (Raf-1) and Signal transducer and activator of transcription 3 (STAT3)." (PMID 31801946, 2019). "We further evaluated two of these candidates by paired-end RNA-seq, from which we identified novel gene fusions, ATG7/RAF1 in pancreatic cancer and BCL6/RAF1 in anaplastic astrocytoma." (PMID 23637631, 2013). "We further characterized the oncogenic relevance of ATG7/RAF1 in pancreatic cancer, using RNAi to knockdown its expression." (PMID 23637631, 2013). "In pancreatic cancer, Ras/Raf-1/MAPK signaling is required for mediating growth factor-induced (such as epidermal growth factor) oncogenic effects." (PMID 22415852, 2012). "Using the MIA PaCa-2 cell line as a model for pancreatic cancer, we showed that TLN-4601 resulted in a time- and concentration-dependent decrease in total Raf-1 protein levels that was associated with a subsequent inhibition of MEK phosphorylation." (PMID 21044336, 2010). "KRB-456 binds with high affinity to KRAS G12D and KRAS G12V, decreases the cellular levels of GTP-bound KRAS, inhibits the binding of KRAS to RAF1 in pancreatic cancer cells, and inhibits in vivo tumor growth of subcutaneous and orthotopic xenografts from patients with pancreatic cancer." (PMID 38051103, 2023). "Furthermore, protein kinase RIPK4 promotes the invasiveness of bladder urothelial carcinoma and pancreatic cancer through nuclear factor‐κB pathway and RAF1/MEK/ERK pathway, respectively." (PMID 31273792, 2020). "Our analysis also uncovered RAF1 rearrangements in pancreatic cancer and in anaplastic astrocytoma." (PMID 23637631, 2013). "For example, among the 8 downregulated genes, RIPK4 (receptor-interacting serine/threonine kinase 4) promotes pancreatic cancer cell migration and invasion by activating RAF1/MEK/ERK signaling; presumably, RIPK4 downregulation in oocytes may also inactivate Erk signaling and impair oocyte quality." (PMID 30786262, 2019). "Some pathways were related to pancreatic cancer (RAF1, CDKN2A, ARHGEF6) and endometrial cancer (PDPK1, RAF1)." (PMID 40018404, 2025). "KRB-456 inhibits KRAS G12D binding to RAF1 and KRAS signaling in cultured human pancreatic cancer cells." (PMID 38051103, 2023). "In pancreatic cancer, miR‐217 was identified to work as a tumor suppressor via directly targeting YWHAG to phosphorylate RAF1 and initiate ERK signaling pathway." (PMID 37626035, 2023). "This is in line with previous studies reporting a role of RAF1 in CRC, lung adenocarcinoma, pancreatic cancer and squamous cell carcinoma." (PMID 37020037, 2023). "Treatment of KRAS G12D-harboring human pancreatic cancer cells with KRB-456 suppresses the cellular levels of KRAS bound to GTP and inhibits the binding of KRAS to RAF1." (PMID 38051103, 2023).
pancreatic cancer (continued). "In pancreatic cancer, RIPK4 can promote cell migration and invasion via the phosphatidylethanolamine binding protein 1 (PEBP1) degradation-induce activation of the RAF1/MEK/ERK signaling pathway." (PMID 35186499, 2022). "ARL4C was identified as RAF1-MEK/ERK pathway-dependent gene in ameloblastoma cell proliferation and osteoclast formation and as down localization of KRAS in pancreatic cancer." (PMID 35785187, 2022). "CERS6-AS1 competitively binds miR-217 to indirectly regulate the expression of YWHAG, which interacts with RAF1 and activates the ERK signaling, thereby accelerating pancreatic cancer progression." (PMID 35927226, 2022). "In contrast, RIPK4 facilitated pancreatic cancer cell migration and invasion via the phosphatidylethanolamine binding protein 1 (PEBP1) degradation-induced activation of the RAF1/MEK/ERK pathway." (PMID 35186499, 2022). "This drug interferes with Raf-1, a member of the RAF/MEK/ERK signaling pathway, which plays a critical role in pancreatic cancer cell proliferation." (PMID 33804613, 2021). "Moreover, microRNA-216a may downregulate RAF1 in pancreatic cancer and increase cell apoptosis." (PMID 33302876, 2020). "Accumulating evidence has demonstrated that RAF1 is an important part of the classical pathway of RAF/MEK/ERK signaling and is highly expressed in multiple cancers including pancreatic cancer." (PMID 32678071, 2020). "Similar results have also been reported when autophagy inhibitors are combined with ERK1/2 inhibitors (ERKi) in patient-derived pancreatic cancer xenograft models and when used in triple combination with the BRAF and CRAF (also known as RAF1) kinase inhibitors in KRAS-mutant cell lines." (PMID 35147163, 2022). "To determine whether RAF kinase rearrangements are recurrent events in pancreatic cancer, we performed break-apart FISH assays for both BRAF and RAF1, on TMAs containing 104 evaluable pancreatic cancer cases." (PMID 23637631, 2013).